INS (insulin)
Diseases named in the same sentence as INS in open-access papers (continued):
Sharing a sentence is not in itself a finding about the gene and the disease.
diabetes (continued). "GLUT4 is a glucose transporter that regulates glucose uptake in skeletal, cardiac muscles and fat cells, increasing insulin sensitivity and improving glucose metabolism, making exercise an early treatment in insulin resistance and diabetes." (PMID 33808424, 2021). "Type 1 diabetes mellitus (T1DM) is a challenging chronic autoimmune condition resulting in a complete cessation of insulin production." (PMID 34907285, 2021). "Basic research on types 1 and 2 diabetes mellitus require early stage studies using beta cells or cell lines, ideally of human origin and with preserved insulin secretion in response to glucose." (PMID 33806355, 2021). "Insulin therapy is necessary for patients with type 2 diabetes mellitus (T2DM) to reach the targeted glycaemic level and prevent complications." (PMID 35002492, 2021). "The discovery of insulin in 1921 and its use to treat diabetes mellitus starting in 1922 decreased the need for other treatment options, but the interest in high-fat, low-carbohydrate diets continued to grow." (PMID 34063366, 2021). "Diabetes is a metabolic disorder induced by the modulation of insulin on glucose metabolism, and the dysfunction and decreased number of islets β-cells are the main causes of T2DM (type 2 diabetes mellitus)." (PMID 34394002, 2021). "Diabetes is a metabolic syndrome rooted in impaired insulin and/or glucagon secretory responses within the pancreatic islets of Langerhans (islets)." (PMID 34045505, 2021). "Diabetes is a severe, long-term (or chronic) disease in the world, defined as a blood glucose profile higher than normal, due to a disturbed insulin secretion or a disturbed insulin effect or usually both." (PMID 34690773, 2021). "89.7% of the women treated diabetes with oral agents, 20.6% used insulin, 8.8% used diet and physical activity, and 1.5% had an insulin pump." (PMID 34769939, 2021). "Of these, one swab was positive; this neonate was born at 35 weeks and 3 days of gestation to a mother with type 2 diabetes mellitus and BMI 40 kg/m2 and treated with insulin." (PMID 34646345, 2021). "The transdifferentiation of adipose-derived mesenchymal stem cells (ADMSCs) into insulin-producing cells (IPCs) is a potential resource for the treatment of diabetes." (PMID 34262902, 2021). "Some of his diabetes pills are stopped, he is advised to start insulin injections and he now receives a weekly MCCA." (PMID 34446490, 2021). "In this type of diabetes the main feature is hyperglycemia, due to the inability of insulin to maintain glucose homeostasis." (PMID 34258010, 2021). "This suggests that sequential failure of insulin homeostasis mechanisms contribute to the onset of diabetes (failure of insulin secretion to remain high) and potentially to the progression of diabetes (failure of insulin clearance to remain low)." (PMID 34206745, 2021). "Diabetes mellitus is a heterogeneous group of diseases characterized by irregular glucose homeostasis and chronic hyperglycemia due to flaw in insulin secretion and activity." (PMID 33763471, 2021). "The treatment of diabetes is mainly based on administration of insulin, the replacement or regeneration of insulin-producing cells, pancreas transplantation." (PMID 34262457, 2021). "Patients with diabetes, previously treated with insulin, present attenuated manifestations of acute glucose fluctuations during AMI, when compared to patients having never received insulin." (PMID 33463901, 2021). "In a cohort of 40 patients with type 1 diabetes mellitus, the doubling of hsa-miR-197-3p and hsa-miR-24-3p level corresponded to a sixfold higher stimulated C-peptide level and 4.2% lower insulin dose–adjusted HbA1c value, respectively." (PMID 34938191, 2021). "MiR-22-3p has been demonstrated to regulate lipid, insulin, and glucose metabolism and play a crucial role in the development of metabolic disorders such as obesity, diabetes and diabetic complications." (PMID 34831451, 2021).
diabetes (continued). "It was interesting to see that the “insulin signaling pathway” was closely connected not only to MetS such as diabetes mellitus but also to CVDs, such as heart diseases." (PMID 35003234, 2021). "PVA and alginate nanofibers modulated obesity, alleviated blood glucose levels, and ameliorated reduced insulin in rats with streptozotocin-induced diabetes." (PMID 34083930, 2021). "Among the various anti-diabetic medications available, intranasal insulin appears to be the most effective means of increasing brain insulin levels, decreasing insulin resistance, a primary problem for many patients suffering from Diabetes Mellitus." (PMID 34540446, 2021). "The reproductive axis is modulated also by metformin, which is the preferred first-line agent in patients with type 2 diabetes mellitus and other insulin resistant states." (PMID 34086261, 2021). "Regarding clinical characteristics, 524 participants (52%) had type 1 diabetes; 723 (72%) used insulin; and 687 (68%) considered their diabetes controlled." (PMID 33439263, 2021). "The protective effect of Galega officinalis extract on the islet apparatus of the pancreas in the case of diabetes was confirmed by investigation of insulin and C-peptide levels, as they are indicators that characterize the functional state of beta cells." (PMID 34572994, 2021). "There is no doubt that blood glucose levels represent a direct risk factor for cardiovascular diseases, of increasing value from prediabetes to diabetes, to insulin-treated diabetes." (PMID 34348706, 2021). "The majority of patients with delirium had been previously diagnosed with arterial hypertension (p = 0.023), chronic heart failure (p = 0.019), chronic kidney disease (p = 0.048) and diabetes treated with insulin (p = 0.002)." (PMID 34279458, 2021). "Glucose-responsive MVLs are expected to provide a desirable and intelligent insulin delivery system with rapid response and good biocompatibility, presenting enormous potential in diabetes management." (PMID 35056918, 2021). "MCTs are involved in maintaining the pH of the interstitial fluid and regulating the binding affinity of insulin to its receptor, which is a potential mechanism for the onset of diabetes." (PMID 34257700, 2021). "A common way to diagnose diabetes consists of measuring the activity of beta cells through glucose metabolism indicators such as plasma glucose, glycated hemoglobin (HbA1c), insulin or C-peptide." (PMID 34944640, 2021). "Oral administration of isomaltulose has previously been shown to result in lower postprandial blood glucose and insulin concentrations in healthy and type 2 diabetes mellitus (T2DM) patients." (PMID 34001166, 2021). "Different types of intermittent fasting reduce body weight and reduce diabetes parameters such as fasting glucose, fasting insulin, HOMA-IR index, and glycated hemoglobin (HbA1c)." (PMID 33826120, 2021). "In our electron microscopy core laboratory, we have previously utilized the hyperleptinemic obese, insulin resistant and diabetic female db/db mouse models of diabetes in order to study the remodeling effects of diabetes in the brain." (PMID 35056324, 2021). "Naringin is abundant in orange peel and has been shown to inhibit DPP-4 in vitro and in vivo and to enhance insulin levels, and thus, is considered an option for the low-cost treatment of diabetes." (PMID 34203048, 2021). "Diabetes is a metabolic disorder characterised by chronic hyperglycaemia, affecting carbohydrate, fat, and protein metabolism leading to abnormal insulin secretion, insulin resistance, or both." (PMID 34335259, 2021). "Insulin treatment is required when patients with diabetes (including newly-detected) and COVID-19 have either a severe or critical clinical course of the disease." (PMID 34173070, 2021). "Diabetes generally develops at relatively early ages and is severe, and most patients need high doses of insulin unless treated with metreleptin." (PMID 34593051, 2021).
diabetes (continued). "In contrast, type 2 diabetes mellitus (T2DM) is characterized by target tissue resistance to the metabolic actions of insulin as well as pancreatic β cell dysfunction." (PMID 34408653, 2021). "While insulin-stimulated glucose uptake via GLUT4 is markedly suppressed in diabetes, glucose uptake can still occur in an insulin-independent manner via GLUT1 and sodium-glucose co-transporter 1 (SGLT1)." (PMID 34831481, 2021). "An early study by Rossetti also indicated that lithium ion is able to restore insulin sensitivity in rats with pancreatectomy-induced diabetes." (PMID 33478120, 2021). "The dynamic variation of insulin secretion is well-handled by the disposition index, which estimates the adequacy of the insulin secretion response to insulin resistance and is highly predictive of diabetes, both in our data and studies of others." (PMID 34206745, 2021). "Duration of diabetes, duration of hypertension, duration of hyperlipidemia, history of cardiovascular disease (CVD), anti-hypertension drugs, use of insulin, family history of diabetes, family history of hypertension, family history of diabetes." (PMID 34977075, 2021). "As expected, insulin secretion estimated with HOMA2-B was lower in the persons with long-term diabetes (%, 63.9 ± 45.9 and 81.1 ± 44.6) as compared to those with new-onset." (PMID 34276762, 2021). "Many guidelines recommend the annual measurement of fasting glucose levels to screen for diabetes or prediabetes, while there are few recommendations for the measurement of fasting insulin levels to screen for them." (PMID 34735502, 2021). "Pre‐pregnancy insulin‐treated diabetes.Diagnosis of fetal growth restriction or hypertensive diseases.Untreated thyroid disease.Hypertension requiring medication.Planning to have the child adopted.Unable to communicate in English or French." (PMID 33463910, 2021). "As insulin mediated suppression of hepatic gluconeogenesis is altered in MetS and type 2 diabetes mellitus, we investigated the effectiveness of GMP to bring this pathway to normality in obesogenic conditions." (PMID 34572325, 2021). "Participants with shorter duration of diabetes were mainly on only OADs, whereas those with long‐standing diabetes were on combination therapies (mainly OADs and insulin)." (PMID 34277959, 2021). "Arbutin, in a Gene Ontology and PPI network study, evolved as the most prospective constituent for 203 target proteins of 48 KEGG pathways regulating immune modulation and insulin secretion to control diabetes." (PMID 34361788, 2021). "Unacylated ghrelin has two useful roles in treating diabetes, namely, improving insulin sensitivity and cellular proliferation." (PMID 34711885, 2021). "The liver plays a major role in insulin resistance and hyperglycemia, concurring with elevated hepatic glucose production and impaired insulin-dependent suppression of glucose uptake during diabetes." (PMID 33925229, 2021). "Respondents stated that diabetes care remained fragmented with insulin and laboratory testing located outside of primary care." (PMID 33777712, 2021). "The sample consisted of 102 T2DM patients on insulin therapy, including 42 males and 60 females, with a mean age of 64.75 years (SD = 9.180) and an average diabetes duration of 10.76 years (SD = 6.702)." (PMID 33561956, 2021). "In this study, we used clustering techniques to identify subgroups of people treated with insulin based upon healthcare resource utilization, select social demographic and clinical characteristics, and diabetes management parameters." (PMID 34238287, 2021). "Diabetes is a complex metabolic disorder resulting either from insulin resistance or an impaired insulin secretion." (PMID 33803588, 2021). "Insulin therapy, which is essential for treating of both type 1 diabetes mellitus and T2DM, plays a vital role in the maintenance of blood glucose level and reduces diabetes complications." (PMID 34497858, 2021).
diabetes (continued). "Diabetes is attributed to defects in insulin secretion and action; disturbance in carbohydrate, fat, and protein metabolism; faulty micro- and macro-vascularization; chronic inflammatory state." (PMID 34589059, 2021). "Race and insulin use were found to be significant moderators of improvements in diabetes distress and improved HbA1c." (PMID 33427667, 2021). "Diabetes is a chronic condition in which the pancreas is unable to produce enough insulin to regulate glucose or the body cells cannot respond to insulin properly." (PMID 34076579, 2021). "We considered including an interaction term for diabetes duration * insulin use, as a proxy for insulin therapy duration." (PMID 33776906, 2021). "The oral disposition index is a β-cell function index and a strong predictor of incident diabetes in Asians with low insulin secretion capacity." (PMID 34359426, 2021). "Insulin crosses the BBB using a saturable transporter, which is regulated by insulin itself and altered by a number of factors including hyperglycemia and diabetes." (PMID 34795562, 2021). "Type I diabetes, which accounts for approximately 10% of all diabetes, is a metabolic perturbation in which the immune system targets the pancreatic beta cells responsible for insulin synthesis." (PMID 34299638, 2021). "The study by Ekanayake & Doolette measured insulin levels in patients with diabetes mellitus during both a single session under hyperbaric and normobaric conditions, and found no change in insulin levels following treatment in either condition." (PMID 34684171, 2021). "Together, these findings indicated that WVBF treatment ameliorated diabetes by increasing insulin secretion in HFD and STZ-induced rats." (PMID 34899339, 2021). "Rosiglitazone is an agonist of PPAR-γ, which has insulin-sensitizing effects in diabetes and neuroprotective effects in neurological disorders." (PMID 34484316, 2021). "We aimed to determine the feasibility of ABE in terms of practicality and acceptability among women with medically (metformin or insulin) treated diabetes." (PMID 34301285, 2021). "Numerous studies have described the beneficial hypoglycemic effect of taurine on increasing insulin availability, through the activation of hepatic glucose accumulation as glycogen and the inhibition of gluconeogenesis in animal models of diabetes." (PMID 36699147, 2021). "NAMPT also contributed to the regulation of insulin secretion in the pancreatic β-cells and diabetes mellitus." (PMID 34041361, 2021). "The dog's condition improved on intensive treatment of diabetes mellitus; daily subcutaneous insulin detemir injection maintained an appropriate blood glucose level over half a year." (PMID 33800028, 2021). "Subsequently, to explore insulin levels and insulin tolerance, which are indicators of diabetes, we measured the fasting insulin level of each group 5 weeks after the treatment." (PMID 33525535, 2021). "Various therapeutic approaches have been used to treat diabetes, including improvement of insulin sensitivity, inhibition of gluconeogenesis, and decreasing glucose absorption from the intestines." (PMID 34207217, 2021). "High blood pressure increases inflammatory markers, such as C-reactive protein, interleukin 6 and adhesion molecules related to the insulin signaling pathway and β-cell function, and further leads to the incident diabetes." (PMID 33926442, 2021). "All three classes of drugs are in widespread clinical use for diabetes because of their ability to augment insulin secretion in people with diabetes." (PMID 34335466, 2021). "Type-2 diabetes mellitus (T2DM) is featured by chronic resistance to insulin and high blood glucose." (PMID 34877187, 2021). "These stem cell-derived β-like cells are capable of sensing blood glucose levels and are also capable of secreting various levels of insulin when transplanted into animal models of diabetes." (PMID 34589059, 2021).
diabetes (continued). "(ii) At the pre-diabetes stage, β-cells compensate for insulin resistance through hypersecretion of insulin." (PMID 33672162, 2021). "The FFAs induced metabolic changes called “lipotoxicity”, has been investigated more on insulin action than on insulin secretion and, the insulin secretion impairment is a major etiological factor for diabetes." (PMID 33320449, 2021). "The treatment of diabetes with exogenous insulin is often problematic due to recurrent hyper-and hypoglycemic episodes." (PMID 33755854, 2021). "Over the last century, diabetes has been treated with subcutaneous insulin, a discovery that enabled patients to forego death from hyperglycemia." (PMID 33573247, 2021). "Contrary to the higher-fat diet in the murine model, diabetes in BB/OKL rats develops by an autoimmune destruction of the insulin-producing pancreatic beta cells." (PMID 33557206, 2021). "The STZ-induced diabetes model in rodents allows for the study of potential interventions based on using β-cell growth factors to enhance functional β-cell mass and insulin secretion." (PMID 33746901, 2021). "In support of these, other studies have suggested the most common indicators of eating pathology in young people with diabetes are elevated HbA1c, disclosure of insulin misuse and body image disturbance." (PMID 34836442, 2021). "Plasma glucose and insulin responses following an oral glucose challenge are representative of glucose tolerance and insulin resistance, key indicators of type 2 diabetes mellitus pathophysiology." (PMID 33788828, 2021). "Questions in the DSMP contemplate different aspects of diabetes self-management, covering five essential self-care domains, namely, exercise, hypoglycemia, diet, blood glucose monitoring, and insulin." (PMID 33905630, 2021). "The presence of DR was associated with higher TyG index (OR = 1.453, P = .001) and longer duration of diabetes (OR = 1.085, P < .001), use of insulin (OR = 3.459, P < .001), and men (OR = 1.459, P = .018)." (PMID 33532603, 2021). "National governments can develop comprehensive policies on selection and pricing of products for diabetes management, ensure insulin and other diabetes supplies are included in UHC packages and remove or regulate mark-ups within the supply chain." (PMID 33483763, 2021). "For diabetes medications (oral and insulin), it was found that the main means of obtaining them in the North was private pharmacies, suggesting regional disparities in access." (PMID 34182965, 2021). "S-allyl cysteine sulfoxide, another constituent found in onion, has been reported to have therapeutic effects on diabetes by stimulating the production and secretion of insulin, interfering with dietary glucose absorption and favoring insulin saving." (PMID 34567150, 2021). "At study initiation, 5095 (50%) CANVAS Program participants were treated with insulin, 2100 (21%) had an HbA1c > 74.9 mmol/mol (9.0%) and the median duration of diabetes was 12.6 years (interquartile interval 8.0–18 years)." (PMID 34448033, 2021). "Type 2 diabetes mellitus (T2DM) is the most common form of diabetes, and is a complex, progressive metabolic condition marked by anomalous insulin production and utilization." (PMID 34071359, 2021). "miRNAs play an important role in insulin secretion, as well as pancreatic islet development, β-cell differentiation, glucolipid metabolism, and many other diabetes-related processes and complications." (PMID 33897780, 2021). "Previous studies showed that MSC transplantation can significantly reduce the insulin dose needed by patients with diabetes, or even help them cease insulin injections." (PMID 33660433, 2021). "Insulin is the only hypoglycemic hormone in the human body and is essential for the treating patients with diabetes to reduce blood glucose levels (BGLs)." (PMID 35056918, 2021).